CSDC2 (cold shock domain containing C2)
Description:
RNA-binding factor which binds specifically to the very 3'-UTR ends of both histone H1 and H3.3 mRNAs, encompassing the polyadenylation signal. Might play a central role in the negative regulation of histone variant synthesis in the developing brain (By similarity).
Synonyms: PIPPIN; dJ347H13.2
Tractability: PROTAC: ubiquitination databases record sites on it; its protein half-life has been measured.
Gene: Protein-coding gene on chromosome 22 (41,560,858 to 41,577,741, forward strand). Ensembl gene ENSG00000172346.
Subcellular location: Nucleus; Cytoplasm
Subcellular location (Human Protein Atlas): Nucleoplasm; Cytosol
Gene Ontology:
Molecular function: protein binding; mRNA 3'-UTR binding; RNA binding; nucleic acid binding
Biological process: regulation of mRNA stability
Cellular component: cytoplasm; nucleus
Genetic constraint (gnomAD): Loss-of-function variants: 8 observed, 12.85 expected, observed/expected ratio (o/e) 0.62, 90% interval 0.36 to 1.12. The upper end of that interval is the gene's LOEUF score, 1.12, which puts it in group 4 of 6, group 1 being the genes least tolerant of losing a copy. Missense variants: 195 observed, 180.72 expected, observed/expected ratio (o/e) 1.08, 90% interval 0.96 to 1.22. Synonymous variants: 96 observed, 78.77 expected, observed/expected ratio (o/e) 1.22, 90% interval 1.03 to 1.44.
Homologues: Orthologues: chimpanzee CSDC2 (100% identical), macaque CSDC2 (99% identical), rat Csdc2 (98% identical), dog CSDC2 (97% identical), pig CSDC2 (97% identical), rabbit CSDC2 (97% identical), guinea pig CSDC2 (97% identical), mouse Csdc2 (97% identical), zebrafish csdc2a (63% identical), zebrafish CSDC2 (61% identical), Drosophila melanogaster CG9705 (45% identical). Paralogues in human: CARHSP1 (60% identical).
Diseases named in the same sentence as CSDC2 in open-access papers:
CSDC2 is named in the same sentence as 11 diseases in open-access papers, as found by Europe PMC text mining. Sharing a sentence is not in itself a finding about the gene and the disease. The quoted sentences say what the papers report.
prostate carcinoma (5 papers, 2015 to 2024). A carcinoma that arises from epithelial cells of the prostate gland. "CSDC2 has been shown to be a potential diagnostic biomarker for early-onset colorectal cancer and prostate cancer." (PMID 35456975, 2022). "For example, transfection of miR-373 in prostate cancer cells induced the expression of E-cadherin and cold shock domain-containing protein C2 (CSDC2) by interacting with reverse complementary sequences at their transcriptional start sites." (PMID 31752361, 2019).
heart failure (2 papers, 2020 to 2022). Inability of the heart to pump blood at an adequate rate to meet tissue metabolic requirements. "Using existing gene expression data in the Gene Expression Omnibus (GEO) database, we screened differentially expressed genes (DEGs) of heart failure and identified six key genes (HMOX2, SERPINA3, LCN6, CSDC2, FREM1, and ZMAT1) by random forest classifier." (PMID 33401250, 2020). "In accordance with adjusted p < 0.05 and |fold-change|>1.5, five RBPs (EIF1AY, RPS4Y1, DDX3Y, RNASE2, and CSDC2) were found in heart failure LV myocardium specimens in comparison to nonfailing controls." (PMID 36313471, 2022). "Of these genes, CSDC2, FREM1, and ZMAT1 have never been associated with heart failure." (PMID 33401250, 2020).
brain tumor (1 paper, 2024). "Previous studies have demonstrated the transcription factor Csdc2’s role in regulating proliferation across various cell types, including brain tumor cells and endometrial stromal cells." (PMID 39125915, 2024).
cervical cancer (1 paper, 2021). A primary or metastatic malignant neoplasm involving the cervix. "The result shows that POLR2J2, RBFOX3, RBMS1, ADARB1, AFF3, CSDC2 and CTIF were down-regulated in most of cervical cancer tissues compared with corresponding normal cervix tissues." (PMID 34863153, 2021).
glioma (1 paper, 2022). A benign or malignant brain and spinal cord tumor that arises from glial cells (astrocytes, oligodendrocytes, ependymal cells). "No published evidence was available as to the roles of the remaining eight underexpressed gene signatures (CHST9, CSDC2, ENHO, FERMT1, IGFN1, LINC00836, MGAT4C and SHANK2) regarding glioma pathogenesis or prognosis." (PMID 35456975, 2022).
Insulin resistance (1 paper, 2025). Increased resistance towards insulin, that is, diminished effectiveness of insulin in reducing blood glucose levels. "Validation using Csdc2-knockout (KO) mice revealed that, after 10 weeks of high-fat diet feeding, Csdc2-KO mice exhibited a 20% greater weight gain than wildtype littermates (p = 0.04, n = 13–18) and developed insulin resistance (p < 0.01)." (PMID 40933310, 2025).
nicotine addiction (1 paper, 2025). "We found genes related to nicotine addiction (CHRNA3, CHRNA4, CHRNA5), neurodegeneration (IREB2), chromosome maintenance (HIST1H2BD), mRNA stability (CSDC2), and transcriptional repression to be potentially affected by the pregnancy maternal smoking phenotype." (PMID 40074595, 2025).
CSDC2 also shares sentences with these, for which no sentence is quoted: colorectal cancer (2 papers); Apathy (1); atherosclerosis (1); depression (1).